TTC9C (tetratricopeptide repeat domain 9C)
Synonyms: MGC29649
Tractability: PROTAC: ubiquitination databases record sites on it; its protein half-life has been measured.
Gene: Protein-coding gene on chromosome 11 (62,727,687 to 62,740,293, forward strand). Ensembl gene ENSG00000162222.
Subcellular location (Human Protein Atlas): Nucleoplasm; Cytosol; Primary cilium tip
Gene Ontology:
Molecular function: protein binding
Genetic constraint (gnomAD): Loss-of-function variants: 14 observed, 22.47 expected, observed/expected ratio (o/e) 0.62, 90% interval 0.41 to 0.97. The upper end of that interval is the gene's LOEUF score, 0.97, which puts it in group 4 of 6, group 1 being the genes least tolerant of losing a copy. Missense variants: 230 observed, 212.47 expected, observed/expected ratio (o/e) 1.08, 90% interval 0.97 to 1.21. Synonymous variants: 88 observed, 87.03 expected, observed/expected ratio (o/e) 1.01, 90% interval 0.85 to 1.21.
Homologues: Orthologues: chimpanzee TTC9C (100% identical), macaque TTC9C (100% identical), rat Ttc9c (97% identical), mouse Ttc9c (95% identical), rabbit TTC9C (95% identical), pig TTC9C (93% identical), dog TTC9C (80% identical), guinea pig TTC9C (78% identical), tropical clawed frog ttc9c (54% identical), zebrafish ttc9c (51% identical), Drosophila melanogaster Fkbp39 (6% identical), Caenorhabditis elegans fkb-4 (5% identical), and 1 more. Paralogues in human: TTC9 (47% identical), TTC9B (46% identical), FKBP6 (20% identical), FKBP4 (19% identical), FKBPL (18% identical), FKBP8 (18% identical), FKBP5 (16% identical), FKBP15 (11% identical), FKBP10 (11% identical), FKBP9 (11% identical), FKBP11 (9% identical), FKBP7 (9% identical), and 6 more.
Diseases named in the same sentence as TTC9C in open-access papers:
TTC9C is named in the same sentence as 2 diseases in open-access papers, as found by Europe PMC text mining. Sharing a sentence is not in itself a finding about the gene and the disease.
TTC9C shares sentences with these, for which no sentence is quoted: mammary carcinoma (1 paper); tumor (1).